CSF3 (colony stimulating factor 3)
Diseases named in the same sentence as CSF3 in open-access papers (continued):
Sharing a sentence is not in itself a finding about the gene and the disease.
asthma (36 papers, 2010 to 2025). "We found that higher genetically proxied expression of PPP1R37 is associated with lower levels of G-CSF/CSF-3, as well as with a lower risk of asthma." (PMID 39794498, 2025). "Although difficult to detect in blood, CSF3 is secreted to a greater extent during infectious or inflammatory conditions including human asthma where it was positively associated with BALF neutrophil numbers and sputum from asthmatic patients." (PMID 35013475, 2022). "CSF3, otherwise identified as G-CSF, exists within the primary 17q12-21 asthma predisposition and exacerbation locus." (PMID 34803456, 2021). "This severe asthma cluster was associated with increased expression of CSF3, CXCL2 and CXCL8, genes usually associated with an “IL‐17 signature”,39 although it was evident that expression of these genes was heterogeneous across the cluster." (PMID 32096290, 2020). "Using integrated results from our GWAS and TWAS findings, we identified an upstream mechanism of yet unknown relevance: higher PPP1R37 gene expression was associated with reduced G-CSF/CSF-3 levels and lower risk of asthma." (PMID 39794498, 2025). "Our results provide genetic support for the concept of targeting G-CSF/CSF-3 in asthma, potentially focusing on patients with neutrophilic asthma." (PMID 39794498, 2025). "Several preclinical studies in asthma models showed that blockage of upstream inductors or the receptor of G-CSF/CSF-3 reduced circulating cytokine levels, alleviated the airway inflammatory response, and improved disease outcome." (PMID 39794498, 2025). "With Mendelian randomization, key cytokines like G-CSF/CSF-3 and CXCL9/MIG are identified as potential causal mediators of asthma and Crohn’s disease, respectively." (PMID 39794498, 2025). "These included associations of higher genetically proxied G-CSF/CSF-3 levels with asthma, lower genetically proxied G-CSF/CSF-3 and higher genetically proxied CXCL9/MIG levels with CD, as well as lower genetically proxied TNF-b levels with MS." (PMID 39794498, 2025). "A transcriptomic sputum dataset from patients with severe asthma showed that CSF3 and CSF3R expression levels showed a positive correlation with the severity of the neutrophilic asthma." (PMID 36428547, 2022). "The expression of CSF3 is higher in poorly controlled asthma, and inhibiting the signaling by neutralizing its receptor, CSF3R, decrease the production of mucus and hyperreactivity in the airway." (PMID 33362771, 2020). "We uncovered several promising tissue-specific regulatory TFs or genes for AD (e.g. ZIC1 and STX1B) and asthma (e.g. CSF3 and IL1RL1) in our case studies." (PMID 29378629, 2018). "We uncovered several promising tissue-specific regulatory TFs or genes for Alzheimer’s disease (e.g. ZIC1 and STX1B) and asthma (e.g. CSF3 and IL1RL1)." (PMID 29378629, 2018). "They found that gene signature profiles of Th2 (IL-13, IL-4) and Th17 (CXCL1, CXCL2, CXCL3, IL-8, CSF3) immune responses were inversely correlated in these samples suggesting a reciprocal regulation of these two pathways in asthma." (PMID 26561853, 2015). "Integrating our data with genetic and clinical data for human disease risk, our analyses suggest potential targets like G-CSF/CSF-3, CXCL9/MIG, and TNF-b for immune-related diseases including asthma, Crohn’s disease, and multiple sclerosis, warranting further exploration in clinical trials." (PMID 39794498, 2025). "Furthermore, G-CSF/CSF-3 levels in the sputum of asthma patients have been suggested as a marker of airway neutrophilic inflammation." (PMID 39794498, 2025). "Using cis-acting variants for G-CSF/CSF-3, CXCL9/MIG, and TNF-b from the UKBB proteomics dataset as instruments, we could confirm significant associations with asthma, CD, and MS, respectively." (PMID 39794498, 2025).
asthma (continued). "Drug target cis-MR using 2 independent proteomics datasets paired with colocalization revealed G-CSF/CSF-3 and CXCL9/MIG as potential causal mediators of asthma and Crohn’s disease, respectively, but also a potentially protective role of TNF-b in multiple sclerosis." (PMID 39794498, 2025). "In a recent study on neutrophilic inflammation in asthma, it was shown that Dexa and IL-17A in combination synergistically induced the expression of the neutrophil promoting cytokine CSF3 and Dexa alone failed to alleviate neutrophilic inflammation." (PMID 32849611, 2020).
ischemia (36 papers, 2006 to 2023). A hypoperfusion of the BLOOD through an organ or tissue caused by a PATHOLOGIC CONSTRICTION or obstruction of its BLOOD VESSELS, or an absence of BLOOD CIRCULATION. "In cerebral ischemia and neonatal hypoxia–ischemia models, CSF3 plays a neuroprotective function against BBB disruption and neuroinflammation to reduce infarct volume and improve neurological outcomes." (PMID 37644514, 2023).
melanoma (34 papers, 2000 to 2025). A malignant, usually aggressive tumor composed of atypical, neoplastic melanocytes. "According to the growing evidence, GCSF (CSF3) and its receptor GCSFR (CSF3R) are overexpressed in numerous malignancies, including melanoma, non-small cell lung cancer, bladder, prostate, and brain tumours." (PMID 38538691, 2024).
ovarian carcinoma (34 papers, 1989 to 2025). A malignant neoplasm originating from the surface ovarian epithelium. "Thus, the function of CSF3 in lymph node metastasis in ovarian cancer still needs further investigation, and CSF3 may be a promising target for the treatment of metastatic lymph nodes." (PMID 36982170, 2023).
glioma (33 papers, 2012 to 2025). A benign or malignant brain and spinal cord tumor that arises from glial cells (astrocytes, oligodendrocytes, ependymal cells). "For instance, IDH1 mutation epigenetically upregulates G-CSF expression in glioma cells by increasing H3K4me3 marks on the CSF3 promoter region, resulting in infiltration of neutrophils, but not PMN-MDSCs." (PMID 39133578, 2024). "We also found that CSF-1, CSF-2, and CSF-3 were all differentially upregulated in the murine glioma microenvironment." (PMID 39272914, 2024). "We identified positive correlation between glioma tumour burden and the magnitude of fold change of the CSF3 gene in plasma, suggesting a potential role for this ccfmRNA transcript as a possible biomarker of tumour burden." (PMID 34643804, 2022). "There was positive correlation between glioma radiographic tumour burden and the magnitude of fold change of the CSF3 gene (r = 0.9813, n = 20, p < 0.001)." (PMID 34643804, 2022). "A highly up-regulated transcript was CSF3 (or GM-CSF), described as an autocrine survival factor in gliomas." (PMID 26291724, 2015). "Furthermore, oHSV-induced NETosis in the contacted co-culture system promoted glioma cell survival in an IGF2BP3/CSF3-dependent manner." (PMID 38167409, 2024). "Indeed, our study demonstrated that BET inhibitors (JQ1, I-BET151) time-dependently inhibited the expression of both IGF2BP3 and CSF3 in glioma cells." (PMID 38167409, 2024). "Additionally, CSF3 promoted, in vitro, proliferation, migration and invasion of glioma cells." (PMID 33066172, 2020). "We also observed that the promotion of glioma cell survival by IGF2BP3-induced NETosis in a contacted co-culture assay could be blocked by CSF3 neutralizing antibodies and enhanced by CSF3 recombinant protein." (PMID 38167409, 2024). "Additionally, oHSV infection upregulated CSF3 (Csf3) mRNA levels in both oHSV-sensitive U87MG and oHSV-resistant GL261 glioma cells." (PMID 38167409, 2024). "It was shown through bioinformatics analysis of publicly accessible TCGA data for GCSF (CSF3) that GCSF expression was not consistent and significant in GBM, however earlier research had found increased GCSF and G-CSFR expression in glioma samples from the Chinese population." (PMID 38538691, 2024).
Splenomegaly (32 papers, 2008 to 2025). Abnormal increased size of the spleen. "As expected, intracardiac inoculation of Csf3-overexpressing EMT6.5 cells into immunocompetent BALB/c mice led to splenomegaly and an increase of host neutrophils in peripheral blood." (PMID 34836954, 2021).
pancreatic cancer (28 papers, 2008 to 2025). "At the transcript level, mRNA expression of Ccl2, Ccl7, Cxcl1, Cxcl3, and Csf2 was markedly downregulated in Ccn1‐deficient pancreatic tumors, whereas Cxcl5, Csf1, and Csf3 expression remained unchanged, and Ccl20 mRNA was elevated." (PMID 40287974, 2025). "In colorectal and pancreatic cancer, the expression of CSF3 is elevated and it increases tumor cell proliferation and migration and shows high immunosuppressive activity." (PMID 36982170, 2023). "In pancreatic tumors, CXCL1 in concert with CSF3 facilitate G-MDSC infiltration and establishment of an immunosuppressive microenvironment that limits T cell frequency and function." (PMID 37988164, 2024).
atherosclerosis (26 papers, 2008 to 2024). A disease characterized by the build-up of fatty material and calcium deposition in the arterial wall resulting in partial or complete occlusion of the arterial lumen. "The downregulation of IL4, CXCL10, MCP1, TNFα, and estradiol and CSF3 upregulation may mediate the adaptation of adiponectin-deficient males to HFD-induced atherosclerosis." (PMID 38201205, 2023). "A meta-analysis suggests that CSF3 administration reduces atherosclerosis, likely by mobilizing progenitor cells." (PMID 38201205, 2023). "The increased expression of CSF3 gene in smooth muscle phenotype transition is one of the important mechanisms of atherosclerosis." (PMID 33777109, 2021).
colorectal cancer (26 papers, 2008 to 2025). A primary or metastatic malignant neoplasm that affects the colon or rectum. "Colony-stimulating factor 3 (CSF3) has been associated with changes to the immune environment in colorectal cancer animal models." (PMID 33606788, 2021). "We found CSF3 (GCSF) gene expression significantly elevated in all four colorectal cancer subtypes compared with adjacent normal tissue." (PMID 36911097, 2023). "Finally, based on a median low verses high gene expression split, high CSF3, MPO, and OLR1 gene expression was associated with reduced disease-specific survival (CSF3 and MPO) and overall survival (ORL1) in colorectal cancer." (PMID 36911097, 2023). "Another research team studied the CSF3/CSF3R signaling in colon and rectal cancers, and results indicated that CSF3/CSF3R expression was correlated with changes in T cell and macrophage signatures and also correlated with genes that are associated with poor colorectal cancer prognosis." (PMID 34729112, 2021). "We utilized publicly available datasets to guide future mechanistic studies of the role CSF3 and its receptor (CSF3R) play in colorectal cancer development and progression." (PMID 33606788, 2021).
autoimmune disease (23 papers, 2010 to 2025). A disorder resulting from loss of function or tissue destruction of an organ or multiple organs, arising from humoral or cellular immune responses of the individual to their own tissue constituents. "The toxic targets of LGT were mainly distributed in the downstream of the pathways, such as LCN2, IL6, IL1B, and CSF3, and ultimately target the inflammatory host defense autoimmunity, proinflammatory activities and other inflammatory reactions and autoimmune diseases." (PMID 36339610, 2022).
Immunodeficiency (23 papers, 2008 to 2025). Failure of the immune system to protect the body adequately from infection, due to the absence or insufficiency of some component process or substance. "In addition, it has recently been demonstrated that mortality in HIV and M. tuberculosis co-infected patients is linked to immune dysfunction of monocytes, especially related to inflammatory mediator production of IL-6, TNFα, and CSF3 and expansion of CD16+CD14+ monocytes." (PMID 29770360, 2018).
bladder cancer (21 papers, 1997 to 2025). "It is undeniable that somatic mutations in the 5’-upstream region of the CSF3 gene caused the overproduction of G-CSF protein in the G-CSF-producing bladder cancer examined in this study." (PMID 37746465, 2023). "In one case of G-CSF-producing bladder cancer, six somatic mutations were detected in the 5’- upstream region of the CSF3 gene." (PMID 37746465, 2023). "In this study, we detected six somatic mutations in the 5’-upstream region of the CSF3 gene in G-CSF-producing bladder cancer." (PMID 37746465, 2023). "In the case of G-CSF-producing bladder cancer (Case 1), six somatic mutations were detected in the 5’-upstream region of the CSF3 gene, but no somatic mutations were found in other regions, including exons." (PMID 37746465, 2023). "In one case of G-CSF-producing bladder cancer, six somatic mutations were detected in the 5’- upstream region of the CSF3 gene, suggesting that they cause G-CSF protein overproduction." (PMID 37746465, 2023). "Here, we observed two cases of G-CSF-producing urothelial cancers (one bladder cancer and one renal pelvic cancer) and analyzed the structures of the CSF3 gene encoding the G-CSF protein and intracytoplasmic domains of TLRs to delineate the mechanism of G-CSF production by those cancer cells." (PMID 37746465, 2023). "No somatic mutations in the CSF3 gene were detected in the other case of GSCF-producing renal pelvic cancer (Case 2) or three cases of G-CSF-nonproducing bladder cancer." (PMID 37746465, 2023). "No somatic mutations in the CSF3 gene were detected in another case of G-CSF-producing renal pelvic cancer and G-CSF-nonproducing bladder cancers." (PMID 37746465, 2023).
liver disease (20 papers, 2010 to 2025). "Notably, the dataset includes many known proteins (IL6, IL10, IFNG, CSF3, PDGFB, CD40, and AFP) and novel proteins associated with liver diseases." (PMID 37209815, 2023). "Also, five proteins (HSP90B1, Protein S100-A9 [S100A9], MMP1, matrix metalloproteinase-9 [MMP9], and CSF3) in the IL17 signaling pathway are in phase III clinical trials for treating solid tumors and have the potential to treat liver diseases." (PMID 37209815, 2023).
Alzheimer disease (19 papers, 2007 to 2025). A progressive, neurodegenerative disease characterized by loss of function and death of nerve cells in several areas of the brain leading to loss of cognitive function such as memory and language. "The decreased levels of CSF3 and other hematopoietic factors have been linked to Alzheimer’s disease (AD) and are, in fact, predictive of conversion from mild cognitive impairment (MCI) to AD." (PMID 37644514, 2023).
bacteremia (19 papers, 2005 to 2025). "CSF-3 was investigated as adjunctive immune therapy for bacterial sepsis, but there was no significant survival benefit." (PMID 28369200, 2017).
Cognitive impairment (19 papers, 2009 to 2024). Abnormal cognition is characterized by deficits in thinking, reasoning, or remembering. "IL-1R2, MATN2 and COLEC12 were associated with cardiorespiratory symptoms, fatigue and anxiety/depression; MATN2, CSF3 and C1QA were elevated in gastrointestinal symptoms and C1QA was elevated in cognitive impairment." (PMID 38589621, 2024).
non-small cell lung carcinoma (19 papers, 2001 to 2024). A group of at least three distinct histological types of lung cancer, including non-small cell squamous cell carcinoma, adenocarcinoma, and large cell carcinoma. "Elevated plasma levels of Csf3 are a poor prognostic indicator in non-small cell lung cancer." (PMID 39338937, 2024).
breast tumor (18 papers, 2007 to 2025). "In a murine model, it has been observed that the development of breast tumors with high metastatic potential is associated with a high accumulation of MDSCs, which could be specifically induced by treatment with G-CSF/Csf3 or by G-CSF secretion from tumor sites." (PMID 36982282, 2023).
metastatic disease (18 papers, 1999 to 2025). "While not significant, a higher percentage of CC patients who had metastatic disease at time of diagnosis had primary tumors in which CSF3 was expressed above the mean (24% high CSF3 as compared to 15% low CSF3, p-value = 0.183)." (PMID 33606788, 2021).
psoriasis (16 papers, 2008 to 2026). An autoimmune condition characterized by red, well-delineated plaques with silvery scales that are usually on the extensor surfaces and scalp. "We found that, upon IL-36 stimulation, IκBζ was actively recruited to the promoter regions of its target genes, including genes encoding for the chemokines Csf3, Cxcl1, and Cxcl2 and the psoriasis-associated antimicrobial proteins Defb4 and S100a9." (PMID 31622280, 2019). "WY14643 treatment significantly downregulated psoriasis‐associated inflammatory cytokines and chemokines (Il17a, Il1b, Cxcl1, Cxcl2, Cxcl3, Cxcl15, and Csf3) as well as the antimicrobial peptides S100a8 and S100a9 in IMQ‐induced skin lesions at the transcriptional level." (PMID 40878384, 2025). "Mechanistically, this psoriasis protection was mediated by IκBζ deficiency in keratinocytes abrogating the induction of specific proinflammatory target genes, including Cxcl5, Cxcl2, Csf2, and Csf3, in response to IL-17A or IL-36." (PMID 31622280, 2019). "Furthermore, inflammatory cytokines relevant to psoriasis pathogenesis, including Il17a, Tnfa, and Il1b, as well as neutrophil‐attracting chemokines, such as Cxcl1 and Csf3, were significantly upregulated at the mRNA level in Fads2‐silenced skin lesions compared to controls." (PMID 40878384, 2025).